CP (ceruloplasmin)
Diseases named in the same sentence as CP in open-access papers (continued):
Sharing a sentence is not in itself a finding about the gene and the disease.
tumor (continued). "Our results extend beyond the current knowledge about CP being a ccRCC tumor marker and shed light on the molecular functions of CP in promoting ccRCC pathogenesis." (PMID 36973268, 2023). "Talazoparib not only reduced tumor growth as a single agent but inhibited tumor growth virtually completely when used in combination with cisplatin (talazoparib alone 824.57 ± 41.2 mm3, p = 0.0061 vs. CP+Talazoparib 333.95 ± 16.65 mm3, p = 0.0018)." (PMID 35321693, 2022). "The mice that received Curcumin and CP combination showed a significant tumor reduction in comparison to the control and Pacli-treated mice." (PMID 35216264, 2022). "All these results can prove that CP-bi-apt has the ability to specifically bind to PD-L1 expressed on tumor cells and CD16 expressed on NK cells." (PMID 35228895, 2022). "With the exception of a few pairwise analyses, namely Treg-Tumor for CP, Treg-Tumor, and Treg-APC for PDAC, more than 50% of the atoms displayed a strong correlation between any two given cell types." (PMID 36541756, 2022). "This phenomenon is due to the ability of both PD-L1-apt and CP-bi-apt to specifically bind to PD-L1, which is highly expressed on tumor cells." (PMID 35228895, 2022). "This suggested that CP was closely related to tumor immunity, cellular proliferation, and migration." (PMID 35232428, 2022). "CP nanodots significantly inhibited the tumor growth of U87MG tumor-bearing mice via CDT-inducing LMP." (PMID 35656308, 2022). "In conclusion, our in vitro results demonstrate for the first time that CP plays a positive role in the efficiency of radiotherapy on GB cells and underlie the idea that radiotherapies may have to be adapted, when necessary, to the CP profile (or status) of tumor cells." (PMID 35918659, 2022). "In GEPIA database, we again proved that CP was low expressed in 461 tumor samples and 558 normal samples (P < 0.05)." (PMID 35232428, 2022). "Based on the results, the investigators concluded that CP plays a vital role in tumour growth, progression and survival in BCa." (PMID 35955727, 2022). "The high affinity of CP-bi-apt toward NK cells and PD-L1 high-expressed tumor cells has been demonstrated." (PMID 35228895, 2022). "Referring to the role of iron in GB cells and in particular stem-type cancer cells, but also at the level of the dynamics of the tumor ecosystem taken as a whole, then the role of CP is undoubtedly much more complex than initially thought." (PMID 35918659, 2022). "DePEGylation of these NP was triggered in the OvCa microenvironment, increasing tumor cell uptake of CP, while maintaining the PEG layer in normal tissues." (PMID 36077371, 2022). "Decreased ceruloplasmin protein levels are also strongly related to several clinicopathological characteristics, such as subtype, age, race and tumor stage." (PMID 34413268, 2021). "Another issue is the phenomena of in vivo transmetallation or transchelation of 89Zr with metal complexing proteins such as transferrin and ceruloplasmin in the liver and kidneys which also increases off-tumor irradiation." (PMID 34621145, 2021). "As shown, CP reduced tumor sizes and suppressed tumor growth in a dose dependent manner, which was consistent with the in vitro experiments." (PMID 34168559, 2021). "Because DNA methylation is important for tumor initiation and progression, we next examined the DNA methylation of ceruloplasmin through the DNMIVD and SurvivalMeth databases." (PMID 34413268, 2021). "Taken together, these results strongly imply a close relationship among ceruloplasmin, the inflammatory response and the tumor microenvironment (TME)." (PMID 34413268, 2021). "Herein, we highlighted the potential prognostic relevance, genetic alterations and methylation status of ceruloplasmin in BRCA and identified ceruloplasmin as a modulator of tumor immune cell infiltration in BRCA patients." (PMID 34413268, 2021).
tumor (continued). "The expression of CP was significantly higher in the tumor group compared with the control group, and the results were exactly the same by paired comparison of samples from the same patient." (PMID 34449964, 2021). "Six overall survival associated genes (ENPP2, ULK1, CP, LURAP1L, HIC1, AKR1C1) were selected to build survival model, of which hub gene AKR1C1 was with high expression and low ferroptosis level in NSCLC tumor." (PMID 34702254, 2021). "The expression of ceruloplasmin was dramatically associated with 48 of 54 and 46 of 54 markers of T cell in BRCA before and after adjustments for tumor purity, respectively." (PMID 34413268, 2021). "As the pathological grade of the tumor increased and the number of lymph node metastases increased, the expression of CP tended to increase." (PMID 34449964, 2021). "We found that ceruloplasmin mRNA and protein expression was remarkably downregulated and correlated with sex, race, tumor clinical stage and pathological grade." (PMID 34413268, 2021). "Recent evidence has indicated that ceruloplasmin is also correlated with tumor development and progression." (PMID 34413268, 2021). "Low-dose CP, which was previously shown to reduce the number of Tregs, enhanced the tumor control achieved by the local treatment and led to high long-term survival rates that confirmed the reduction in metastatic load." (PMID 32766128, 2020). "In these seven pairs of human specimens, higher levels of CP mRNA were found in 4 out of the 7 tumor samples compared with the normal samples, as determined by RNA-seq." (PMID 32708433, 2020). "Cu is known to influence tumor growth through the stimulation of several cuproenzymes, including Ceruloplasmin (CP), MEK1/2, and Cytochrome C Oxidase (CCO/COX), which are associated with various biological functions." (PMID 32709883, 2020). "4T1-bearing mice were treated with CP 1 day before the first polyICPEI injection (30 μg/60 μl), which is 4 days prior to DaRT insertion (activity = 65 kBq), at a time in which tumor size was ~24 mm3." (PMID 32766128, 2020). "Higher levels of CP mRNA expression were detected in the 4 out of 7-paired tumor/normal lung tissues and the 7 datasets from the Oncomine® database." (PMID 32708433, 2020). "The results revealed that the expression of CP was significantly higher in tumor tissues compared with adjacent non-tumor tissues." (PMID 32708433, 2020). "PolyICPEI+CP+inert seed or DaRT+vehicle significantly retarded tumor development compared to inert+vehicle control (pt−test < 0.05, on the day of resection)." (PMID 32766128, 2020). "Both recombinant and synthetic forms of CP-dn-ATF5 effectively promote apoptosis of a wide variety of tumor cells in vitro and in vivo." (PMID 31551409, 2019). "To address this, we first over-expressed FLAG-survivin in T98G tumor cells and then assessed the capacity of CP-dn-ATF5 to promote their death." (PMID 31551409, 2019). "In this study, we found that ceruloplasmin was overexpressed 3.38 fold in tumor tissue compared with normal bile duct tissue." (PMID 28423673, 2017). "AGR2 was a major common molecule in the media of LuCaP 70CR and 10-076 CP as indicated by strong immunostaining of the respective tumor tissue." (PMID 27283903, 2016). "Strikingly, fluctuations in CP protein levels in the urine correlated with the tumor burdens in the mice." (PMID 26133466, 2015). "Because the effects of metformin and CP were quite similar in terms of receptor down-regulation and IGF-1R signaling pathway inhibition, we then asked if there are any additive anti-tumor effects when combining metformin with CP." (PMID 26287334, 2015). "This approach can facilitate future studies of micrometastasis, where the migration of tumor cells can be identified by gene delivery of luciferase to secondary sites by the released CP Env virus." (PMID 23767896, 2013). "In blood, development of the tumour produced an increase in ceruloplasmin and a decrease in iron-transferrin." (PMID 187210, 1976).
tumor (continued). "Among the females, tumor size was inversely correlated with serum iron (ρ = −0.37, p = 0.046) and positively correlated with ceruloplasmin (ρ = 0.42, p = 0.021), which correlated also with the pT stage (ρ = 0.55, p = 0.002) and with the TNM stage (ρ = 0.36, p = 0.049)." (PMID 40507970, 2025). "The lack of a statistically significant response to FX and GC may be in part explained by resistance from the tumor because the tumor had progressed before resection after the patient was treated with some of the compounds (5-FU in FX and CP in GC)." (PMID 40367160, 2025). "Following the clustering with Harmony and PCA, the significant differences in tumour‐CS or stroma‐CS in each cluster between CP‐i and CP‐s samples were evaluated by the Wilcoxon test, indicating that regardless of tumour‐CS or stroma‐CS, the values in all the clusters of CP‐s were greater than CP‐i." (PMID 40697100, 2025). "Moreover, the protein overlap status in the tumour and stroma was consistent among the CP‐s and CP‐i samples." (PMID 40697100, 2025). "This indicates that while both formulations effectively enhance CBD absorption and anti-cancer activity, CP-liposomes may offer a slight advantage regarding permeability and tumor reduction." (PMID 41304881, 2025). "In the analysis of drug resistance features using spatial proteomics, comparison of the spot proteomes in the tumour‐like and stroma‐like regions sampled in continuous mode between CP‐i and CP‐s resulted in 505 CP‐related DEPs with high reliability and stability in the experiment." (PMID 40697100, 2025). "Compared with the S group and the S + CP group, tumours in the S + CPB group were smaller, which might imply a certain antitumour effect of BP nanosheets." (PMID 38388544, 2024). "Additionally, LINC02936 was consistently extremely expressed in tumor tissues, > 60 years old, G3, dead group, and had poor survival outcome, which was consistent with CP in TCGA-UCEC." (PMID 38385087, 2024). "CP has also been identified as a tumor promoter in various malignancies." (PMID 38339384, 2024). "Accordingly, elevated CP plasma levels at IDS may indicate an increased risk of early recurrence and potentially more aggressive tumor biology." (PMID 39337685, 2024). "Given the critical role of CP in copper transport, it is unclear whether abnormal CP expression promotes tumor progression by reprogramming copper metabolism." (PMID 38385087, 2024). "Interestingly, there were different expression patterns in the other areas, as CP as well as IGFBP2 were expressed more toward the cellular part of the tumor, whereas LOX was expressed more in the peripheral vascular zones." (PMID 38339384, 2024). "Similarly, we also observed an association between CP and TGM2-FN1 signaling between tumor cells and myofibroblasts." (PMID 36973268, 2023). "Probably, abrogating the interaction of CP with LF within that complex might amplify the anti-tumor effect of LF/8OA." (PMID 38069040, 2023). "Therefore, high CP expression in tumor cells inhibits ferroptosis, which reduces tumor cell death and promotes tumor progression." (PMID 37637428, 2023). "Interestingly, low ceruloplasmin expression correlates with a favorable prognosis and tumor immune cell infiltration in BC patients." (PMID 37461536, 2023). "Moreover, interestingly, HA‐decorated CP/Ad‐SS‐GD/RNP nanocomplexes (HA/CP/Ad‐SS‐GD/RNP) targeting the KRAS gene were evaluated in an SW480 tumor‐bearing nude mouse model." (PMID 37166046, 2023). "We have demonstrated that CP-bi-apt could mediate the binding of NK cells to tumor cells at the cellular level." (PMID 35228895, 2022). "In addition, several of the proteins related to the regulation of iron metabolism, including lactoferrin (LTF), transferrin receptors 1/2 (TFR1, TFR2), transferrin (TF), and ceruloplasmin (CP), have been identified as tumor markers." (PMID 35028002, 2022).
tumor (continued). "We then further evaluated whether the prepared CP-bi-apt could promote in vivo antitumor effect by the recruitment of NK cells to tumor site and then blocking PD-1/PD-L1 axis." (PMID 35228895, 2022). "However, when ICG-labeled NK cells and CP-bi-apt were simultaneously injected, the fluorescence at the tumor site significantly increased, implying that more NK cells were recruited into the tumor tissue." (PMID 35228895, 2022). "We further investigated the in vivo biodistribution of CP-bi-apt in tumor-bearing nude mice." (PMID 35228895, 2022). "Interestingly, only the ferroptosis pathway was the most relevant Biological Process to the tumor and three genes were mapped to the ferroptosis pathway, which included transferrin (TF), ceruloplasmin (CP), and ferritin light chain (FTL)." (PMID 35340268, 2022). "Immunohistochemistry elucidated that CP was under-expressed in tumor tissues." (PMID 35232428, 2022). "Afterward, we further investigated whether CP-bi-apt could promote the accumulation of NK cells in tumor sites." (PMID 35228895, 2022). "Additionally, we explored the correlations of ceruloplasmin expression with infiltration patterns for different tumor-infiltrating immune cells in BRCA." (PMID 34413268, 2021). "There was a significant reduction in average tumor volume of CP-treated groups (130.45 ± 16.50 mm3 for 625 mg/kg CP high-dosage group, 206.54 ± 15.25 mm3 for 300 mg/kg CP low-dosage group) compared with that of the untreated group (498.95 ± 100.06 mm3) of mice bearing HepG2-HBx cells." (PMID 34168559, 2021). "Untreated tumor cells rapidly spread away from the original microinjection position in zebrafish of the control group; In contrast, CP administration not only suppressed primary tumor marked by Dil staining, but also tended to reduce the spreading inclination toward the whole zebrafish body." (PMID 34168559, 2021). "In addition, the inhibition of tumor growth was most pronounced in CP@NP‐cRGD group, suggesting the better active targeting property of cRGD‐coated NPs." (PMID 33511016, 2021). "H&E staining also showed that CP suppressed the tumor growth in zebrafish." (PMID 34168559, 2021). "On the other hand, studies have shown that CP also plays an important role in angiogenesis, while many reports have shown that CP content is high in the serum of patients with malignant tumors and in tumor tissues including the kidney." (PMID 34449964, 2021). "Interestingly, extra fragment (80 kDa) was observed across all tumor patients with low 140 kDa ceruloplasmin isoform expression." (PMID 32620920, 2020). "Ten days post DaRT, for example, tumor volume in the control (inert+vehicle) group was 2.5-fold higher than DaRT only group (DaRT+vehicle), and 3.1-fold higher than that in the immunotherapy-only group (polyICPEI+CP+inert)." (PMID 32766128, 2020). "Furthermore, oncogenic properties of the LINC00176/BCL3/CP axis were also demonstrated by tumour formation in vivo generated upon injecting cells in nude mice." (PMID 31668012, 2020). "In contrast, neither plasmid nor penetratin delivered dn-ATF5 appears to affect survival of non-transformed cells and there have been no evident side-effects in mice treated with either the recombinant or synthetic forms of CP-dn-ATF5 at doses that suppress tumor growth." (PMID 31551409, 2019). "In this context, we thus asked whether the capacity of CP-dn-ATF5 to deplete survivin is necessary for its ability to promote tumor cell death or whether this agent also has additional death-promoting activities." (PMID 31551409, 2019). "Here, we hypothesized that AKT and HBV CP mutations cooperate to disrupt SKP2, which accelerates tumour proliferation and angiogenesis while inhibiting tumour apoptosis." (PMID 27779207, 2016).
tumor (continued). "A similar observation of the high transfection efficiency of CP was also reported by Hu and co-workers, who found that CP not only has a higher transfection efficiency than PEI 25 kDa in vitro but can also effectively deliver the CCL22 gene to reduce the tumor growth rate in vivo." (PMID 25961282, 2015). "This nearly “silent” receptor down-regulation phenomenon might partially explain the anti-tumor effects of CP." (PMID 26287334, 2015). "Incubation of TMV CP fused to T cell tumor-specific epitopes elicited immune responses and protected against tumor challenge in mice, indicating that the virus could act as an antigen carrier and induce an adequate immune response." (PMID 24745025, 2014). "Our finding that genes involved in SMC differentiation and organ specificity were down-regulated in CP stromal cells is in line with the hypothesis that stromal cell differentiation in tumor is abnormal." (PMID 19737398, 2009). "The hepatocytic nature of the cHCC cell line is further indicated by the activity of the liver-specific enzyme ALT and the expression of hepatocyte markers, like serum albumin, ceruloplasmin, and alpha-fetoprotein, as it is also the case for the human tumor liver cell line HepG2." (PMID 15566568, 2004). "The effect of CP on survival after primary-tumour excision on Day 10 was observed." (PMID 7387830, 1980). "TS analysis revealed conserved tissue architecture across CP response groups, whereas CS mapping revealed pretreatment metabolic reprogramming (rather than proliferation) as the defining feature of chemo‐resistant tumours, challenging current resistance paradigms." (PMID 40697100, 2025). "Furthermore, we observed CP levels according to tumor origins." (PMID 39337685, 2024). "We next evaluated whether CP-d/n-ATF5 could inhibit tumor growth and metastasis in vivo." (PMID 38014922, 2023). "Furthermore, we revealed the spatial heterogeneity of CP using spatial transcriptomics and CP’s potential role in mediating tumor-stroma interactions in ccRCC with the snRNA-seq data of ccRCC tumor tissue and RNA-seq data of cells in which CP was suppressed by shRNA." (PMID 36973268, 2023). "Furthermore, the inhibition of CP loop can promote ferroptosis and radiosensitivity by disrupting Cu-Fe homeostasis, demonstrating that CP may be a new target and treatment strategy for overcoming tumor radioresistance." (PMID 38021154, 2023). "Further glycosyl-modified CP-liposomes (GMCP-liposomes) were prepared by the incorporation of n-Dodecyl β-D-maltoside (Mal) into the liposomal bilayer with glucose residue anchored on the surface to act as a ligand targeting the GLUT1 receptor highly expressed on tumor cells." (PMID 35893789, 2022). "Niraparib (alone 1086.25 ± 76.2 mm3, p = 0.013 vs. CP+Niraparib 1037.48 ± 77.9 mm3, p = 0.034) and rucaparib (alone 1233.75 ± 61.65 mm3, p = 0.046 vs. CP+Rucaparib 1023.54 ± 64.21 mm3, p = 0.037) reduced tumor growth to a similar extent singly as well as in combination with cisplatin." (PMID 35321693, 2022). "Moreover, the tumor weight differences analysis found that PG could slow down tumor growth evidently as CP." (PMID 35496272, 2022). "Furthermore, in vivo results showed that combining CP@NP‐cRGD with AZD9291 significantly decreased the growth of NSCLC AZD9291 resistance‐tumor xenografts and exhibited excellent targeting properties, sustained releasing potential, good stability, and low toxicity." (PMID 33511016, 2021). "Furthermore, a previous study reported that iron metabolism-related genes FPN1 and CP might participate in tumor immune microenvironment of ACC." (PMID 34335745, 2021). "CP media differed chiefly from LuCaP media in the presence of molecules secreted by the cancer-associated stromal cells and other minor cell types of the primary tumor, which were absent in the xenografts." (PMID 27283903, 2016). "Then, we validated whether the CP level corresponded to the tumor burdens in these mice." (PMID 26133466, 2015).